CCNE2 (cyclin E2)
Diseases named in the same sentence as CCNE2 in open-access papers (continued):
Sharing a sentence is not in itself a finding about the gene and the disease.
tumor (continued). "The vast majority of genes were equally expressed in tumor and non-tumoral, control pituitary glands, including CCNL1, CCNE2, CCNB2, CCNA1, CDK18, CDK19 and CDK20." (PMID 35260162, 2022). "By contrast, in primary tumours high levels of CCNE1, but not CCNE2, predict a shorter relapse-free interval of tamoxifen-treated patients." (PMID 20180967, 2010). "However, the observed increase of CCNE2 mRNA levels in the diseased group compared to the healthy control group, which are reported to be undetectable in normal quiescent cells arrested in G0, is in conflict with the supposed non-proliferative nature of circulating tumor cells." (PMID 21129172, 2010). "Interestingly, cyclin E2 becomes expressed at high levels in immortalised mouse embryonic fibroblasts derived from E2F1 knockout animals, and is also expressed at high levels in chemically-induced tumours derived from the same mice, without concurrent changes to cyclin E1 expression." (PMID 20180967, 2010).
cancer (97 papers, 2008 to 2026). A tumor composed of atypical neoplastic, often pleomorphic cells that invade other tissues. "We here identify that cyclin E2 is one such driver, as it associates with the preRCs of cancer cells, its upregulation increases genome doubling and its depletion attenuates the induction of DNA rereplication." (PMID 32823571, 2020). "Despite rigorous effort, the underlying mechanisms of CCNE2 involved in the tumorigenesis and cancer progression are still largely unknown." (PMID 32487779, 2020). "Certain studies have shown that miR-449 could directly target and switch off the expression of GMNN, MET, CCNE2 and another cancer-related genes, the majority of which are associated with the cell cycle, by syncretizing with the 3′UTR of target genes." (PMID 25202363, 2014). "Therefore, even though it appears that CCNE2 might play a role in cancer progression, its underlying molecular mechanism is unknown." (PMID 26265440, 2015). "Transcriptomic analysis revealed the upregulation of cell cycle- (MKI67, CCNE2 etc.)and cancer-related genes (SYK, MCM2 etc.), and GSEA confirmed the enrichment of Rb-related pathways." (PMID 41535675, 2026). "AOH1160 repressed the expression of CDK1, CCNB1, CDK2 and CCNE2 to arrest the cell cycle at G2/M phase, thus blocking the promotion of cancer cell mitosis." (PMID 40313621, 2025). "Cyclin E2, a major rate-limiting factor in the G1/S transition, is overexpressed in various tumors and functions by promoting cancer." (PMID 39890802, 2025). "Aberrant expression of cyclin D1 and cyclin E2 has been reported in various human cancers and correlates with the clinical outcome." (PMID 36012128, 2022). "Mechanistically, we showed that miR‐34c regulates Notch signaling and other cancer related pathways by targeting multiple genes (CCNE2, E2F2, E2F5, and HDAC1)." (PMID 35509638, 2022). "Subsequently, after knockdown of hsa_circ_0000073, the marked downregulation in messenger RNA and protein expression of two cancer-related genes, CCNE2 and MDM2, was verified by qRT-PCR and WB." (PMID 34568326, 2021). "CCNE1 and CCNE2 amplification, as well as increased mRNA expression, have been also correlated with whole genome doublings in human cancers." (PMID 34901021, 2021). "We found, in contrast, that MCM proteins bind abundantly to cyclin E2 on chromatin, providing a possible mechanism to assist preRC formation in cancer." (PMID 32823571, 2020). "Both CCNE1 and CCNE2 are reported as related to proliferation and genomic instability, which are two features of genome doubled cancers." (PMID 32823571, 2020). "In several lines of cancer, CCNE2 expression is modulated by miRNA or long non-coding (lncRNA), which play a key role to influence tumorigenesis and progression." (PMID 31767812, 2019). "As a result, Cyclin E2, a direct target of all these microRNAs is upregulated, promoting cancer growth and migration." (PMID 29180617, 2017). "In contrast, the genes encoding cyclin-A1, -B1, -E1 and -E2, i.e. Ccna1, Ccnb1, Ccne1 and Ccne2, were up-regulated in malignant tumors." (PMID 25900242, 2015). "CCNE2 (cyclin E2) was proved to be the key regulator of clavatustide B-induced G1-S transition blocking in several cancer cell lines by using real-time PCR." (PMID 24879544, 2014). "Our results shown that epigenetic expression of LEPREL1 inhibitS the cancer cell proliferation by arresting the G1/S phase via downregulation of cell cycle regulatory proteins, including Cyclin A2 and Cyclin E2." (PMID 24319452, 2013).
cancer (continued). "By contrast, HPV+ cancers up-regulated, relative to HPV-HNC, a much larger set of cell cycle-specific genes such as cyclin E2 (CCNE2; G1 associated), cyclin B1 (CCNB1; G2 associated), and multiple MCMs." (PMID 21447181, 2011). "Further evidence from cell culture models indicates that cyclin E2 has similar proliferative effects to cyclin E1 in cancer cells." (PMID 20180967, 2010). "For example, HPV-positive cancers, compared to HPV-negative, upregulated a much larger set of cell cycle-specific genes such cyclin E2 (G1 associated), cyclin B1 (G2 associated) and multiple MCMs." (PMID 19036130, 2008). "It remains to be seen whether redundancies in the CDK2/CCNE1 pathway (CDK1 for CDK2, CCNE2 for CCNE1) observed in normal cells pose another challenge of targeting this pathway in cancers." (PMID 36572991, 2023). "CCNE2 is an important component in cell proliferation and cancer, which may explain the anti-proliferative activity of ST2825." (PMID 37749630, 2023). "CCNE2 plays a role in cell cycle progression and is aberrantly expressed in human cancers." (PMID 35200555, 2022). "Only in N0, DNA (excision-) repair (involved genes: CDKN1A, PPM1D, and DDB2) was predicted to be a downstream function, while molecular networks in N2+ were associated with cancer, as well as injury and abnormalities (among others, downregulation of MSH6, CCNE2, and CHUK)." (PMID 36068491, 2022). "Correlation analysis and cell biological experiments showed that NR1H4 expression was positively associated with Cyclin E2 and CDK2, which indicated NR1H4 may play its oncogenic role in cancer by regulating CCNE2." (PMID 36123627, 2022). "As previously reported, CCNE2, which is frequently observed in proliferation, or migration in various kinds of cancers, is one of the two regulatory subunits of cyclin-dependent kinase 2 and could regulate the progression from G1 to S phase in cells." (PMID 34568326, 2021). "We then examined whether CCNE1 and CCNE2 expression has prognostic value depending on whether a cancer had undergone whole genome doubling." (PMID 32823571, 2020). "When the cohort is split in to non-genome doubled and genome doubled cancers, CCNE2 amplification is associated with poor prognosis in those cancers that have not undergone genome doubling." (PMID 32823571, 2020). "CCNE2 was significantly higher in genome doubled cancers (p < 0.0051)." (PMID 32823571, 2020). "CCNE2 is involved in regulating the cancer cycle, apoptosis, and metastasis." (PMID 33614501, 2020). "This suggests a model where high cyclin E2 in non-genome doubled cancers increases the risk of genome doubling, leading to genome doubled cancers with high cyclin E2 expression." (PMID 32823571, 2020). "A recent study shows that CCNE2 is also involved in regulating cancer apoptosis and migration." (PMID 33614501, 2020). "We observed overexpression of CCNE2 and increased motility in cancer cells overexpressing uc." (PMID 29180617, 2017). "Our digital PCR data show that uc.339 is expressed much less than miR-339, -663b, and -95 in cancer cells, raising the concern on whether uc.339 can affect the expression of CCNE2 by modulating its targeting miRNAs." (PMID 29180617, 2017). "Moreover, activation of CCNE2 can increase cancer cell migration, adhesion, invasion, proliferation and metastasis." (PMID 28176879, 2017). "Cyclin E2 down-regulation has also been reported as an important effect of anti-cancer drugs." (PMID 23181557, 2012). "Oncogenes such as MYC, AKT1, AKT2, cyclins CCNA2, CCNB1, CCNB2, CCNE1, CCNE2 and cyclin-dependent kinases CDK1 and CDK4, which were upregulated under androgen treatment, exhibited a significantly reduced expression following PVT1 knockdown, thereby modulating cancer-associated oncogenic pathways." (PMID 41792045, 2026). "Therefore, we supposed si-NR1H4 suppressed malignant phenotype of ccRCC cells due to the downregulation of CCNE2/CDK2 which could help cancer cells switch from G0/G1 to S phase." (PMID 36123627, 2022).
cancer (continued). "However, the underlying mechanisms of how CCNE2 contributes to tumorigenesis and cancer progression is not clear and remains to be elucidated." (PMID 32487779, 2020). "However, the regulatory role of CircCCNB1/miR449-a/CCNE2 in cancer requires further investigation." (PMID 31767812, 2019). "Similarly, it was previously seen in cancer cells in which treatment with a drug, AS1411 (a quadruplex-forming oligonucleotide aptamer) led to the decreased association of PRMT5 with known gene promoters (cyclin E2, tumor suppressor genes)." (PMID 28678843, 2017). "Significantly increased expression levels of CCNE2 have been observed in various tumors such as those of the lung, breast, pancreas, and nasopharyngx, and have been shown to play important roles in the proliferation, invasion, metastasis, and poor prognosis of these cancers." (PMID 28056099, 2017). "However, given the potential differences in function in endoreplication and other processes, cyclin E1 and cyclin E2 may have distinct attributes that contribute to cancer progression." (PMID 20180967, 2010). "CCNE2 could be a potential target for the rational development of new cancer drugs." (PMID 18304324, 2008). "In order to maintain cancer cell proliferation, HLXB9 upregulates genes that are involved in the G1-S transition of the cell cycle, such as Cyclin E1 (CCNE1) and Cyclin E2 (CCNE2)." (PMID 39239563, 2024). "The expression of certain cell cycle genes (CCNB1, CCNE1, CCNE2, and FOXM1) was race-dependent in several cancer types and correlated with significant survival differences." (PMID 37345032, 2023). "Only a small subset of these genes was differentially expressed in multiple carcinomas, including genes involved in cell cycle progression such as CCNB1, CCNE1, CCNE2, and FOXM1." (PMID 37345032, 2023). "PPI analysis showed potential interactions between three cancer driver genes (AKT1, KRAS, and PIK3CA) and candidate genes (CCNE2, RAD51, and NEIL3)." (PMID 36233194, 2022). "Meanwhile, the inhibition of FOXM1 repressed the expression of CDK6, CCND1, CDK2, CCNE2, E2F2, and CDC25A to arrest the cell cycle at G2 phase, which blocks the promotion of cancer-cell mitosis." (PMID 34880209, 2021). "Among all cyclin genes analyzed, CCNA2, CCNE2, CCNB2, CCNB1, CCNF, and CCNE1 were most elevated in the included cancers." (PMID 33996604, 2021). "Altogether, the results of our study indicate that MTA commits RCM‐1 cancer cells toward their differentiation into dome tissue via the down‐regulation and dysfunction of CDC25A and possibly of CCNE2, the key cell‐cycle regulators in the G1 phase." (PMID 33048473, 2020). "Cyclin E2 (CCNE2) is identified as the second member of E-type CDKs, which contributes to the G1/S phase transition, cell proliferation, tumorigenesis and cancer progression." (PMID 32487779, 2020). "We demonstrate that cyclin E2 localises with core preRC (pre-replication complex) proteins (MCM2, MCM7) on the chromatin of cancer cells." (PMID 32823571, 2020). "Many regulators including CBP/p300, ATAD2, Cyclin E2, SWI/SNF and NPAT play important roles in cancer survival and proliferation." (PMID 29212286, 2017). "Introduction of miR-34b/c into cancer cells leads to the downregulation of candidate target genes, including MET, CDK4, cyclin E2 (CCNE2), and MYC." (PMID 24348513, 2013).
cancer (continued). "The mechanisms involved in the in vitro anti-cancer activity of SF5 seem to be similar to those of EEPp, leading to the inhibition of cyclin E2 gene expression and resulting in cell cycle arrest in the G1 phase." (PMID 23181557, 2012). "While eravacycline and omadacycline have never been tested for their potential anti-cancer activity, tigecycline, which was approved as an antibiotic in 2005, demonstrated possible anti-cancer activity and, in the case of PDAC, exerted its action via downregulating of CCNE2." (PMID 38647152, 2024). "This methodology has the potential for identifying the critical regulatory genes involved in maintaining cell cycle coherent oscillation, such as CDC25C, CCNE2, KPNA2, etc., which may be the new targets in cancer." (PMID 38353329, 2024). "In addition, NF-κB downstream effectors, such as CCND1, CCNE2, MET, VEGFA, CD44 and CD133, contribute to cancer proliferation, metastasis and stemness, and their expression is regulated by PCDH1." (PMID 35864095, 2022). "Moreover, the gene microarray indicated knockdown of PSMC2 notably changed a number of genes, especially some cancer related genes including ITGA6, FN1, CCND1, CCNE2 and TGFβR2, and whose expression changes were further confirmed by western blotting." (PMID 27888613, 2017). "Interestingly, both CCNE2 and MAL2 are located on chromosome 8q, a region which is frequently increased in copy number in breast and other cancer types, and one of the most important target genes affected by gains and amplifications of 8q is the MYC oncogene." (PMID 21129172, 2010). "In addition, CCNE2, PIK3CB, ITGAV, RB1, and BIRC2 involved in cancer pathway were also affected." (PMID 28567416, 2017). "In addition, application of NS1643 to a non-transformed breast cell line (MCF10A) did not have any effect either on cyclin E2 or cell proliferation rate (data not shown) suggesting that the effect of NS1643 is specific to hERG1 positive cancer cells." (PMID 25596745, 2015). "NF-κB has also been an important target for anti-cancer treatment and this study demonstrated that SF5 exposure inhibited NF-κB translocation to the nucleus, probably inhibiting the expression of specific NF-κB targets, as here demonstrated for cyclin E2 and c-myc." (PMID 23181557, 2012). "A panel of six genes (CCNE2, DKFZp762E1312, EMP2, MAL2, PPIC and SLC6A8) were over-expressed in cancer cell lines and were absent in healthy women." (PMID 29132396, 2017). "Therefore, we suppose that the detection of CCNE2 and MAL2 transcripts in the blood of cancer patients is indicative for CTC presence (which had not been verified by immunocytochemistry)." (PMID 21129172, 2010). "Importantly, SIRT3 has delactylation activity, the removal of lactylation from the non-histone proteins on Cyclin E2 (CCNE2), a key cell cycle protein reported to be essential for cancer progression, is catalyzed by SIRT3 to suppress the proliferation, migration, and invasion of cancer cells." (PMID 40164592, 2025).
infection (7 papers, 2010 to 2024). The state of being infected such as from the introduction of a foreign agent such as serum, vaccine, antigenic substance or organism. "AsPC‐1 and HPAC cells were stably infected with lenti‐virus encoding CCNE2, and Western blot revealed that CCNE2 expression was recovered after infection." (PMID 32141702, 2020). "Here, we show the virus also induces expression of cyclin E2 early in infection, then moderates cyclin E2 protein levels through targeting by miR-US25-1." (PMID 20585629, 2010). "Interestingly, transcript levels of genes regulating DNA replication and cell cycle progression (Cdc25c, Fosb, Cdkn3, cyclin E2, Chaf1b, Cdt1) were specifically increased in SkMCs and neurons after infection." (PMID 28775382, 2017). "CUL1 and CCNE1, two S phase target genes, whose mRNA levels were upregulated at various time points after DTMUV infection, while the mRNA levels of RBX1, SKP2 and CCNE2 were decreased at all the time points, moreover, CCNE2 was time-dependently downregulated." (PMID 32897243, 2020). "In contrast, genes in a cluster known to regulate nucleoplasm architecture such as HDAC11, CCNE2, and POLI reduced infection upon depletion." (PMID 24874089, 2014).
adenocarcinoma (1 paper, 2020). A common cancer characterized by the presence of malignant glandular cells. "Through the Kaplan-Meier plotter database, we found that high expression of CARM1 or CCNE2 was highly associated with shorter 10-year overall survival of NSCLC (adenocarcinoma) patients, implying the oncogenic roles of CARM1 and CCNE2 in promoting the progression of NSCLC." (PMID 32487779, 2020). "Notably, high expression of CARM1 (Cutoff value was 262; P < 0.01) or CCNE2 (Cutoff value was 228; P < 0.01) was highly associated with shorter 10-year overall survival of NSCLC (adenocarcinoma) patients, implying the oncogenic roles of CARM1 and CCNE2 in promoting the progression of NSCLC." (PMID 32487779, 2020).
CCNE2 also shares sentences with these, for which no sentence is quoted: melanoma (2 papers); stomach cancer (2); Alzheimer disease (1); astrocytoma (1); autoimmune disease (1); breast (1); Breast Invasive Carcinoma (1); cardiovascular disease (1); chordoma (1); chronic lymphocytic leukemia (1); Cirrhosis (1); dysplasia (1); Fanconi anemia (1); graft versus host disease (1); Hodgkins lymphoma (1); inflammatory bowel disease (1); lung fibrosis (1); MALT lymphoma (1); metastatic cancers (1); Obesity (1); oral squamous cell carcinoma (1); pancreatic ductal adenocarcinoma (1); renal fibrosis (1); rheumatoid arthritis (1); small cell lung carcinoma (1); squamous cell carcinoma (1); thyroid tumor (1).